FBXO15 (F-box protein 15)
Description:
Substrate-recognition component of the SCF (SKP1-CUL1-F-box protein)-type E3 ubiquitin ligase complex.
Synonyms: FBX15; MGC39671
Tractability: No criterion of Open Targets' tractability assessment is met for any kind of drug.
Gene: Protein-coding gene on chromosome 18 (74,073,344 to 74,147,867, reverse strand). Ensembl gene ENSG00000141665.
Pathways (Reactome):
Immune System: Antigen processing: Ubiquitination & Proteasome degradation
Metabolism of proteins: Neddylation
Gene Ontology:
Molecular function: protein binding
Biological process: SCF-dependent proteasomal ubiquitin-dependent protein catabolic process
Cellular component: cytosol; SCF ubiquitin ligase complex
Genetic constraint (gnomAD): Loss-of-function variants: 33 observed, 55.34 expected, observed/expected ratio (o/e) 0.6, 90% interval 0.45 to 0.8. The upper end of that interval is the gene's LOEUF score, 0.8, which puts it in group 3 of 6, group 1 being the genes least tolerant of losing a copy. Missense variants: 591 observed, 646.29 expected, observed/expected ratio (o/e) 0.91, 90% interval 0.85 to 0.98. Synonymous variants: 250 observed, 236 expected, observed/expected ratio (o/e) 1.06, 90% interval 0.95 to 1.18.
Homologues: Orthologues: chimpanzee FBXO15 (99% identical), macaque FBXO15 (94% identical), dog FBXO15 (76% identical), pig FBXO15 (75% identical), guinea pig FBXO15 (75% identical), rat Fbxo15 (70% identical), mouse Fbxo15 (56% identical), tropical clawed frog fbxo15 (41% identical), zebrafish zgc:161973 (30% identical), zebrafish fbxo15 (28% identical). Paralogues in human: FBXW5 (15% identical).
Diseases named in the same sentence as FBXO15 in open-access papers:
FBXO15 is named in the same sentence as 13 diseases in open-access papers, as found by Europe PMC text mining. Sharing a sentence is not in itself a finding about the gene and the disease. The quoted sentences say what the papers report.
autism (2 papers, 2016 to 2021). Persistent deficits in social interaction and communication and interaction as well as a markedly restricted repertoire of activity and interest as well as repetitive patterns of behavior. "Furthermore, if the TCF4, NETO1, and FBXO15 genes were in the region of hemizygosity, the risk of autism increased significantly." (PMID 35056323, 2021). "Forty-three percent of patients with 18q deletion were categorised to be at risk of autism and the likelihood was significantly increased when TCF4, NETO1 and FBXO15 were included in the region of hemizygosity." (PMID 27271878, 2016).
depression (2 papers, 2020 to 2022). "Only four SNV variants were considered to have high penetrance for depression: OGDHL rs2293239, TBX1 rs41298838, IL16 rs201457933, and FBXO15 rs79499419." (PMID 35370858, 2022). "Compared with TBX1, IL-16, and FBXO15, we found that OGDHL was strongly associated with depressive disorders in a range of different aspects." (PMID 35370858, 2022). "Nonetheless, considering the uncertain relevance of IL-16 and FBXO15 for depressive disorders, we did not prioritize them in the functional investigation." (PMID 35370858, 2022).
breast carcinoma (1 paper, 2021). "To better understand the pathophysiological functions of the identified F-boxes (FBXO43, FBXO15, and CCNF) in BRCA, we performed specific-RNAi knockdown in breast carcinoma cells to assess the potential loss/gain-of-functions." (PMID 34201347, 2021). "Interestingly, among all 71 F-box family members, there are four F-boxes (FBXO43, FBXO15, FBXL8, and CCNF) with significantly upregulated mRNA levels in breast carcinoma tissues." (PMID 34201347, 2021).
cancer (4 papers, 2016 to 2021). A tumor composed of atypical neoplastic, often pleomorphic cells that invade other tissues. "FBXO15 knockdown led to increased P-gp expression and transport activity in both cancer cell lines." (PMID 29997495, 2018). "In this study, we retrospectively profiled the transcriptome of BRCA tissues and found a notable upregulation of four SCFF-box E3 ligases (FBXL8, FBXO43, FBXO15, and CCNF) in the carcinoma tissues." (PMID 34201347, 2021).
FBXO15 also shares sentences with these, for which no sentence is quoted: aspergillosis (1 paper); colorectal cancer (1); immune deficiencies (1); infection (1); insomnia (1); neurodegenerative disease (1); Proteinopathies (1); Sepsis (1); tumor (1).